MDM2 (MDM2 proto-oncogene)
Diseases named in the same sentence as MDM2 in open-access papers (continued):
Sharing a sentence is not in itself a finding about the gene and the disease.
breast carcinoma (continued). "The elevated MDM2 level was found in many cancers, such as lung cancer, breast cancer, liver cancer, oesophagogastric cancer, colorectal cancer, sarcomas, osteosarcomas, gliomas, melanomas and hematopoietic malignancies." (PMID 37185737, 2023). "It is known that MDM2 overexpressed in many types of cancer (lung cancer, breast cancer, liver cancer, oesophagogastric cancer and colorectal cancer) can act as an oncogene." (PMID 37185737, 2023). "Knockdown studies on breast cancer cell lines establish the role of MDM2 in upregulating the expression while downregulating the expression of MMP-3, MMP-10 and MMP-13." (PMID 37314603, 2023). "This further strengthens its use as an effective treatment in advanced ER+ breast cancers where MDM2 is often overexpressed." (PMID 36923534, 2023). "In a similar manner, the combination of MDM2 together with some PIK3C3 inhibitors in breast cancer was an attractive option." (PMID 35249548, 2022). "We found that ZLM-7 upregulated 14-3-3 sigma expression but downregulated MDM2 expression in breast cancer cells." (PMID 35890172, 2022). "Overexpressed MDM2 in tumors has been shown to correlate to a poor prognosis, especially in patients diagnosed with breast cancers." (PMID 35890172, 2022). "MDM2 ligase, coupled with inhibitors of the targets BCL2L1, BRD4, CDK9, PLK1 and MCL1 in stomach cancer, and MDM2 with PIK3C3 inhibitors in breast cancer seemed to be the best therapeutic construction." (PMID 35249548, 2022). "We interrogated the candidates for well-developed drug targets and identified MDM2 as the top druggable gene whose knock-down significantly reduced cell viability in the two GATA3-mutant breast cancer cell lines (MCF-7 and KPL-1)." (PMID 35440675, 2022).
breast carcinoma (continued). "The qPCR analysis was conveyed for gene expression and the result revealed that the 14-3-3 sigma expression in both breast cancer cells was decreased while the MDM2 expression was increased in comparison with those in normal breast epithelial cells." (PMID 35890172, 2022). "We further analyzed the function of MDM2 in breast cancer cells, in terms of cell proliferation and apoptosis." (PMID 35890172, 2022). "Upregulated MDM2 was detected in many malignancies such as lung cancer, breast cancer, liver cancer, esophagogastric cancer, colorectal cancer, and etc.." (PMID 35468874, 2022). "MDM2 ligase coupled with inhibitors of the targets BCL2, BRD4, CDK9, PLK1 and MCL1 in stomach tumor, and MDM2 with PIK3C3 inhibitors in breast cancer, seems to be the best therapeutic strategy." (PMID 35249548, 2022). "MDM2 is elevated in a multiple of cancer cell types, including colorectal adenocarcinoma, breast cancer, lung cancer, and osteosarcoma." (PMID 36038536, 2022). "When assessing enrichment pathways in the MDM2/MYC amplification group by GSEA within grade III ER+HER2− breast cancer, we identified that grade III ER+HER2− patients with MDM2/MYC amplification were enriched in cell cycle KEGG pathway." (PMID 34146382, 2022). "MDM2 overexpression can be observed in many cancers such as lung cancer, breast cancer, liver cancer, esophagogastric cancer and colorectal cancer." (PMID 36551770, 2022). "Our results thus support MDM2 as a therapeutic target in the substantial fraction of ER-positive, GATA3-deficient breast cancer." (PMID 35440675, 2022). "Human breast cancer cells were transfected with p-MDM2 and the success of transfection was validated by qPCR and Western blotting assay, where increased gene and protein expressions were observed in transfected cells." (PMID 35890172, 2022). "By using the successfully established 14-3-3 sigma knockdown cells and the 14-3-3 sigma overexpression cells, we next explored the potential regulatory relationship between 14-3-3 sigma and MDM2 in breast cancer." (PMID 35890172, 2022). "The objective of this study was to explore the potential regulatory machinery of ZLM-7 on the 14-3-3 sigma/MDM2 signal axis and to provide new insights for the therapeutic targets of breast cancer." (PMID 35890172, 2022). "MDM2 overexpression was also detected in many malignancies including lung cancer, breast cancer, liver cancer, esophagogastric cancer, colorectal cancer, etc.." (PMID 35468874, 2022). "In our study we investigated the MDM2 (rs2279744, rs937283, rs937282) and MDM4 (rs1380576, rs4245739) single nucleotide polymorphisms in 100 Lithuanian breast cancer patients." (PMID 33669778, 2021).
breast carcinoma (continued). "In this study, we demonstrated the antitumor efficacy of ALRN-6924, a dual inhibitor of Mdm4 and Mdm2, in ER+ breast cancer cell line models and identified significant synergy with combination of ALRN-6924 with chemotherapeutic agents." (PMID 33663585, 2021). "MDM2 amplification and overexpression has been observed in many tumour types including breast cancer." (PMID 34695137, 2021). "Although the MDM2 gene is rarely amplified in ER+ breast cancer, relatively high levels of MDM2 protein are commonly observed, occurring in at least 38% of cases." (PMID 34804982, 2021). "In accordance with the proposed mechanism for how MDM2 can induce breast cancer resistance to CDK4/6 inhibitors, preclinical studies have evaluated the effects of MDM2 inhibitors on the growth of CDK4/6-resistant tumors." (PMID 34830174, 2021). "ARF-BP1 was found upregulated in breast cancer, and in about 40% of patients with a subset of liposarcoma that showed MDM2 overexpression." (PMID 33670160, 2021). "Five SNPs across MDM2 (rs2279744, rs937283, rs937282) and MDM4 (rs1380576, rs4245739) genes were evaluated for associations with breast cancer phenotype." (PMID 33669778, 2021). "FBXO22 has also been shown to target MDM2 proto-oncogene (HDM2) for ubiquitination and degradation, thereby inhibiting breast cancer invasion and metastasis." (PMID 35141150, 2021). "6% MDM2 amplification in breast carcinoma has been reported in another study of over 2000 breast cancer cases." (PMID 34695137, 2021). "These complex interactions and functional feedback loops demand a degree of caution when considering the use of MDM2 inhibitors to treat ER+ breast cancer." (PMID 34804982, 2021). "Estrogen treatment in breast cancer cell lines has been shown to overexpress MDM2 and promote carcinogenesis." (PMID 34635759, 2021). "Reports have shown significant correlation with failure of anti‐PD‐1/PD‐L1 agents and MDM2 amplification, but few of these have been specific to breast cancer." (PMID 33314633, 2021). "In this study, we showed that overexpression of the MDM2 gene clearly correlates with decreased overall survival of breast cancer patients, but only in the case of the HER2 molecular cancer subtype." (PMID 34572735, 2021). "The data indicated that overexpression of TRIM31 inhibited the growth of breast cancer cells, and this effect was rescued by MDM2 overexpression." (PMID 34650049, 2021). "Previously, we and others demonstrated that MDM2 overexpression in non-small cell lung cancer and breast cancer decreased overall patient survival after treatment." (PMID 34572735, 2021).
breast carcinoma (continued). "Accordingly, we applied qRT-PCR to quantify the expression of MDM2 mRNA in ≈100 human breast tumor samples as well as in 16 breast cancer and four untransformed mammary epithelial cell lines with predetermined rs150550023 genotypes." (PMID 33202864, 2020). "Important publications propose MDM2 as a promising therapeutic drug to treat human cancer, including breast cancer." (PMID 32456234, 2020). "To extend our observations to a clinicopathologically-relevant context, we then analyzed the protein expression levels of ECT2, USP7, and MDM2 with breast carcinoma samples and histologically normal mammary tissues." (PMID 32929379, 2020). "Mechanistically, ECT2 together with USP7, forms a positive feedback loop to control the expression of each other, and the reciprocal stabilization of the two molecules fuels oncogenic MDM2 in breast cancer." (PMID 32929379, 2020). "Researches have reported that MDM2 overexpression modulates the angiogenesis-related gene expression profile of prostate cancer cells and MDM2 inhibitors exerted anti- angiogenesis effects in human breast cancer and neuroblastoma." (PMID 33680941, 2020). "This circuit eventually promotes breast cancer cell survival, at least, through sustaining the expression of oncogenic protein MDM2." (PMID 32929379, 2020). "Overexpression of MDM2 is related to an inferior prognosis in various tumors, such as stomach, lung, esophagus and breast cancer; leukemia; glioblastoma; liposarcoma; and other treatment-resistant tumors." (PMID 32359357, 2020). "Collectively, these results suggested that ECT2/USP7 circuit is potentially linked to breast carcinogenesis, and ECT2 coordinates with USP7 to promote breast cancer cell survival, at least, via activating oncogenic MDM2." (PMID 32929379, 2020). "We found that, when staining was scored according to the mean intensity extent of immunopositivity, ECT2 and USP7 together with MDM2 were highly expressed in breast carcinoma samples, and the levels of their expression correlated with each other." (PMID 32929379, 2020).
breast carcinoma (continued). "Our results demonstrate that MDM2 inhibition is a rational target for novel therapeutic strategies in the setting of treatment-resistant breast cancer." (PMID 32787886, 2020). "A 50% reduction in the final tumor volume was confirmed after animals were killed, indicating that MDM2 drives estrogen-mediated ERα+ breast cancer cell proliferation in vivo." (PMID 30642351, 2019). "Like SNP309 in the MDM2 gene, SNPs in the MDMX gene are apparently correlated with early age-at-diagnosis and risk of breast cancer dependent on the ER-expression status." (PMID 30956778, 2019). "Similar to melanoma cells, the expression of Mdm2 and MdmX is often increased in breast carcinoma cells." (PMID 31181622, 2019). "This is the first report showing that the expression of MDM2 in ERα+ breast cancer and TNBC can result in different tumor-promoting outcomes." (PMID 30642351, 2019). "MDM2 is a multifunctional oncoprotein and is overexpressed in various human cancers, including human breast cancer." (PMID 31428819, 2019). "It is conceivable that specific allelic variants of MDM2 and MDMX add another layer to this fine-tuned crosstalk in breast cancer." (PMID 30956778, 2019). "Numerous other mechanisms contribute to increased MDM2 expression and/or activity in breast cancer, such as ERα-expression, downregulation of p14ARF, TGF1-b1-expression, as well as, expression of MDMX isoforms." (PMID 30956778, 2019). "The genomic datasets from the datasets of cBioportal for Cancer Genomics revealed that MDM2 overexpression can be detected in many malignancies like lung cancer, breast cancer, liver cancer, esophagogastric cancer and colorectal cancer." (PMID 31440117, 2019). "We previously showed that MDM2 provides an estrogen-mediated proliferative advantage to breast cancer cells and disrupts acini formation by increasing phosphorylation of Rb and elevating E2F1 protein levels." (PMID 30642351, 2019). "The expression of FKBP12 was decreased in breast cancer tissues, and there was a significant correlation between FKBP12 loss and MDM2 overexpression." (PMID 31428819, 2019). "In this study, we compared different subtypes of breast cancer cells, and we were interested in the comparative expression of MDM2, MDMX, and CXCR4 in the different contexts." (PMID 30642351, 2019).